HTATIP2 (HIV-1 Tat interactive protein 2)
Diseases named in the same sentence as HTATIP2 in open-access papers (continued):
Sharing a sentence is not in itself a finding about the gene and the disease.
tumor (continued). "Aspirin did not inhibit the proliferation of HCC cells, but it decreased the invasiveness of HCC with lower expression of HTATIP2 and increased expression of a set of markers, indicating a mesenchymal-to-epithelial transition in tumor cells." (PMID 23741443, 2013). "Our previous study confirmed that sorafenib promotes invasiveness and metastasis of HCC in xenograft models, as indicated by increased intrahepatic metastasis (IHM), lung metastasis, and circulating tumor cells of tumors with higher expression of HTATIP2." (PMID 23741443, 2013). "Increased VEGFA mRNA (Vegfa) production has been reported in Htatip2-silenced tumor cells." (PMID 37847559, 2023). "Furthermore, analysis of the HTATIP2 knockout mouse led to the recognition of its role as a tumor suppressor gene." (PMID 36817429, 2023). "Tumor metabolic reprogramming is regulated by HTATIP2, which functions as a tumor suppressor." (PMID 37965333, 2023). "However, immunohistochemical evaluation of MPG in the treatment naïve GBM also identified tumors with both nuclear and cytoplasmic MPG expression patterns that displayed a wide range of HTATIP2 expression reflecting tumor heterogeneity." (PMID 37491696, 2023). "The tumor-promoting effect of the absent HTATIP2 expression was associated with HIF2α upregulation and enhancement of c-Myc oncogenic activity through the HIF2α regulated β-catenin/c-Myc/MCL-1 pathway." (PMID 32545251, 2020). "Our previous studies have also demonstrated that sorafenib promotes invasiveness and metastasis of HCC through downregulation of HIV-1 Tat interactive protein 2 (HTATIP2) using animal tumor models; nonetheless, the clinical significance of the latter finding has not been fully elucidated." (PMID 25008315, 2014). "This synergistic anti-tumor effect can be attributed to up-regulation of HTATIP2." (PMID 23741443, 2013). "However, some studies of HTATIP2 suggest that it plays a role in tumor suppress progression." (PMID 34745221, 2021). "HTATIP2 has a reported inhibitory function on importin β‐mediated cytoplasmic–nuclear shuttling of cargo proteins, suggesting that epigenetic silencing may affect tumor biology by disturbing the balance of nuclear/cytoplasmic localization of a subset of critical proteins." (PMID 37491696, 2023). "Subsequently, we applied RT-PCR to detect the expression level of GAPDH, GNPNAT1, HTATIP2, MFI2, PKP2, RGS20, and CHRDL1 in these 10 tumor tissues." (PMID 35186082, 2022). "DYNLT3 (dynein light chain Tctex-type 3) and HTATIP2 (HIV-1 Tat interactive protein 2) inhibit proliferation and survival, respectively, suggesting tumor suppressor activity." (PMID 22848398, 2012). "According to reports, when tumor cells experience hypoglycemic conditions, the absence of HTATIP2 expression can enhance the cells’ metabolic adaptation to glucose limitation." (PMID 37965333, 2023). "In this study we demonstrated that the absence of HTATIP2 expression in A549 human NSCLC cells resulted in accelerated tumor growth despite stalled tumor neovascularization and reduced tumor oxygenation, and lowered tumor sensitivity to sorafenib treatment." (PMID 32545251, 2020). "Although it is well accepted that the absent HTATIP2 expression is associated with the increased susceptibility to tumorigenesis and enhanced tumor invasion and metastasis, the impact of HTATIP2 deficiency in tumor cells on tumor adaptation to hypoxia remains unclear." (PMID 32545251, 2020). "Overall, the data suggest that the absence of HTATIP2 expression fine-tunes tumor adaptation to hypoxia and subsequent response to treatment through HIF2α and its target genes." (PMID 32545251, 2020). "HIV-1 Tat Interactive Protein 2 (HTATIP2) is a tumor suppressor, of which reduced or absent expression is associated with increased susceptibility to tumorigenesis and enhanced tumor invasion and metastasis." (PMID 32545251, 2020).
tumor (continued). "The 30-kDa Tat-interacting protein (TIP30), also known as HTATIP2 or CC3, was initially identified as a tumor suppressor and is involved in many biological events at various stages of tumor progression, such as tumor initiation, cell proliferation, angiogenesis, metastasis and chemoresistance." (PMID 30642057, 2019). "TIP30, also called CC3 or HTATIP2, is a putative tumor suppressor initially identified by a differential display analysis of mRNA in highly metastatic human variant small cell lung carcinoma (v-SCLC), versus less metastatic classic small cell lung carcinoma (c-SCLC) cell lines." (PMID 25544767, 2015). "Immunostaining of HTATIP2 was mainly distributed in the cytoplasm of tumor cells or hepatocytes (data not shown)." (PMID 25008315, 2014). "For example, DKK1, HTATIP2, HBP1, MXI1 and CASP7, all bound by RBM47 and upregulated upon RBM47 reintroduction, have known tumor suppressive functions." (PMID 24898756, 2014). "The discovery of the roles of HTATIP2/TIP30 in apoptosis and tumor suppression, especially in controlling the expression of genes involved in apoptosis and metastasis suppression, indicates that there is a signal pathway facilitated by HTATIP2/TIP30 and its associated factors." (PMID 23800048, 2013). "In another study, researchers demonstrated that the absence of HTATIP2 expression in A549 human NSCLC cells resulted in accelerated tumor growth despite stalled tumor neovascularization and reduced tumor oxygenation, and lowered tumor sensitivity to sorafenib treatment." (PMID 34688245, 2021). "However, whether the absent expression of HTATIP2 is a tumor-promoting factor that acts through improving tumor adaptation to hypoxia is unclear." (PMID 32545251, 2020). "Collectively, the data suggest that the absence of HTATIP2 expression promotes an aggressive tumor phenotype by enhancing the HIF2α-regulated β-catenin/c-Myc/MCL-1 signaling, increasing the susceptibility of tumors to sorafenib-activated EMT process, and improving tumor metabolic plasticity." (PMID 32545251, 2020). "Taken together, the data demonstrated that the absent expression of HTATIP2 in A549 cells resulted in an aggressive tumor phenotype, marked by rapid growth, poor oxygenation and decreased sensitivity to sorafenib treatment, which was not attributable to the decreased sorafenib distribution in tumor." (PMID 32545251, 2020). "Therefore, aspirin could be used to improve the efficacy of sorafenib, regardless of HTATIP2 expression in HCC tumor cells." (PMID 23741443, 2013).
cancer (24 papers, 2009 to 2025). A tumor composed of atypical neoplastic, often pleomorphic cells that invade other tissues. "Loss of HTATIP2 expression has been associated with a broad spectrum of cancer cell type‐dependent biological effects such as loss of pro‐apoptotic properties, enhanced invasion and metastatic potential, and enhanced liver carcinogenesis." (PMID 37491696, 2023). "In addition to being a marker of poor prognosis in a variety of human cancer, HTATIP2 downregulation was found to be associated with the acquired drug resistance." (PMID 32545251, 2020). "HTATIP2 expression is frequently down-regulated in cancers, which is in agreement with our result that knock-down increases T cell proliferation in the absence of exogenous growth signals." (PMID 36817429, 2023). "In PC-3 cells, we also identified Htatip2 and Tert deregulated expression in response to OPNc overexpression, which are also gene products that mediate cell survival, metastasis and cancer recurrence." (PMID 24928374, 2014). "HTATIP2/TIP30 displays a serine-threonine kinase activity that can phosphorylate the carboxyl terminal domain of RNA polymerase II in a TAT-dependent manner, suggesting that HTATIP2/TIP30 is a potential target for human cancer treatment." (PMID 23800048, 2013). "The HTATIP2/TIP30 level was significantly higher in the cancer group than in the control group (1.84 ± 0.82 versus 0.57 ± 0.13 ng/ml, mean ± SD)." (PMID 23800048, 2013). "The HTATIP2/TIP30 level was significantly higher in the cancer group than in the control group (1.8363 ± 0.8177 (minimum: 0.82 to maximum: 3.67) versus 0.5659 ± 0.127 (minimum: 0.36 to maximum: 0.79) ng/ml, respectively)." (PMID 23800048, 2013). "Almost all the relevant studies have focused on the role of HTATIP2/TIP30 in cancer pathogenesis." (PMID 34688245, 2021). "Despite the evidence that decreased HTATIP2 expression is indicative of the development of cancer chemoresistance, the exact mechanism remains unclear." (PMID 32545251, 2020). "Moreover, our study shows that the methylation levels of selected genes, such as RASSF1 and HTATIP2, change with the cancer stages, indicating their potential values in the prognosis of ESCC." (PMID 27893424, 2017). "Clinical studies regarding the status of HTATIP2/TIP30 expression in cancer patients are limited." (PMID 23800048, 2013). "Therefore, we hypothesized that epigenetic silencing of HTATIP2 may modulate nuclear transport of cancer‐relevant proteins in an importin β‐dependent manner." (PMID 37491696, 2023). "Moreover, a study on the role of HTATIP2 in cancer metabolism demonstrated that silencing of HTATIP2 in HeLa cells cultured under low glucose condition improved their metabolic adaptation to glucose limitation by maintaining high levels of c-Myc and the M2 isoform of pyruvate kinase." (PMID 32545251, 2020). "Some of these upregulated genes, including HTATIP2, PRG4, and HFE, were previously reported to be involved in cancer metastasis." (PMID 31718700, 2019). "EP300, ISGF3G, STAT1, and STAT3 are up regulated in 8/13 of cancer models, while ATM, BAX, BCL2L11, HTATIP2, LGALS3, MAPK1, and TP73L are down regulated in half of cancer models." (PMID 19402918, 2009).
HTATIP2 also shares sentences with these, for which no sentence is quoted: lung carcinoma (8 papers); colon cancer (4); esophageal cancer (4); laryngeal carcinoma (4); lung adenocarcinoma (4); small cell lung carcinoma (4); gastric cancer (3); melanoma (3); neuroblastoma (3); non-small cell lung carcinoma (3); heart failure (2); lymph node metastasis (2); prostate carcinoma (2); adenocarcinoma (1); advanced heart failure (1); brain tumor (1); cardiomyopathy (1); cervical cancer (1); dilated cardiomyopathy (1); esophageal squamous cell carcinoma (1); gallbladder adenocarcinoma (1); gynecological cancers (1); hepatoblastoma (1); hypertrophic cardiomyopathy (1); hypertrophy (1); infection (1); large cell carcinoma (1); limb ischemia (1); Nephroblastoma (1); pancreatic adenocarcinoma (1).
A further 6 diseases each share a sentence with HTATIP2 in 1 paper.